CENPS (centromere protein S)
Description:
DNA-binding component of the Fanconi anemia (FA) core complex. Required for the normal activation of the FA pathway, leading to monoubiquitination of the FANCI-FANCD2 complex in response to DNA damage, cellular resistance to DNA cross-linking drugs, and prevention of chromosomal breakage. In complex with CENPX (MHF heterodimer), crucial cofactor for FANCM in both binding and ATP-dependent remodeling of DNA. Stabilizes FANCM. In complex with CENPX and FANCM (but not other FANC proteins), rapidly recruited to blocked forks and promotes gene conversion at blocked replication forks. In complex with CENPT, CENPW and CENPX (CENP-T-W-S-X heterotetramer), involved in the formation of a functional kinetochore outer plate, which is essential for kinetochore-microtubule attachment and faithful mitotic progression. As a component of MHF and CENP-T-W-S-X complexes, binds DNA and bends it to form a nucleosome-like structure. DNA-binding function is fulfilled in the presence of CENPX, with the following preference for DNA substates: Holliday junction > double-stranded > splay arm > single-stranded. Does not bind DNA on its own.
Synonyms: CENP-S; APITD1; FAAP16; MHF1
Tractability: PROTAC: ubiquitination databases record sites on it.
Gene: Protein-coding gene on chromosome 1 (10,430,433 to 10,442,808, forward strand). Ensembl gene ENSG00000175279.
Subcellular location: Nucleus; Chromosome, centromere; Chromosome, centromere, kinetochore
Pathways (Reactome):
Cell Cycle: Amplification of signal from unattached kinetochores via a MAD2 inhibitory signal; Deposition of new CENPA-containing nucleosomes at the centromere; EML4 and NUDC in mitotic spindle formation; Mitotic Prometaphase; Resolution of Sister Chromatid Cohesion; Separation of Sister Chromatids
DNA Repair: Fanconi Anemia Pathway
Immune System: PKR-mediated signaling
Signal Transduction: RHO GTPases Activate Formins
Gene Ontology:
Molecular function: chromatin binding; DNA binding; double-stranded DNA binding; protein binding; protein heterodimerization activity
Biological process: DNA damage response; DNA repair; interstrand cross-link repair; replication fork processing; resolution of meiotic recombination intermediates; chromosome segregation; positive regulation of protein ubiquitination
Cellular component: chromatin; FANCM-MHF complex; Fanconi anaemia nuclear complex; inner kinetochore; nucleus; cytosol; nucleoplasm; chromosome, centromeric region
Genetic constraint (gnomAD): Loss-of-function variants: 16 observed, 16.41 expected, observed/expected ratio (o/e) 0.97, 90% interval 0.66 to 1.48. The upper end of that interval is the gene's LOEUF score, 1.48, which puts it in group 6 of 6, group 1 being the genes least tolerant of losing a copy. Missense variants: 160 observed, 159.1 expected, observed/expected ratio (o/e) 1.01, 90% interval 0.88 to 1.15. Synonymous variants: 49 observed, 54.72 expected, observed/expected ratio (o/e) 0.9, 90% interval 0.71 to 1.14.
Homologues: Orthologues: pig CENPS (83% identical), guinea pig CENPS (78% identical), dog CENPS (75% identical), rabbit CENPS (75% identical), mouse Cenps (70% identical), macaque CENPS (70% identical), tropical clawed frog cenps (61% identical), zebrafish cenps (49% identical), chimpanzee CENPS (33% identical). Paralogues in human: CORT (9% identical).
Diseases named in the same sentence as CENPS in open-access papers:
CENPS is named in the same sentence as 33 diseases in open-access papers, as found by Europe PMC text mining. Sharing a sentence is not in itself a finding about the gene and the disease. The quoted sentences say what the papers report.
Fanconi anemia (8 papers, 2013 to 2025). Fanconi anemia (FA) is a hereditary DNA repair disorder characterized by progressive pancytopenia with bone marrow failure, variable congenital malformations and predisposition to develop hematological or solid tumors. "Among these, FANCD2, FANCI and other proteins of the Fanconi Anemia complex were highly enriched, including APITD1, also known as CENPS, which promotes mono-ubiquitination of FANCD2-FANCI in response to DNA damage." (PMID 31180492, 2019).
CREST syndrome (3 papers, 2020 to 2022). "CENPs, such as CENPA and CENPB, have been discovered to be immune autoantigens of systemic scleroderma." (PMID 36644760, 2022).
neuroblastoma (3 papers, 2004 to 2021). Neuroblastoma (NB) is the most common solid, extracranial childhood tumor.
calcinosis (2 papers, 2010 to 2020). Deposition of calcium in the tissues. "Carrying out the same low temperature treatment, the oocytes were stained with CREST (anticentromere antibody, autoimmune sera from patients with calcinosis, Raynaud phenomenon, esophageal dysmotility, sclerodactyly, and telangiectasia, a marker of CENPs at the kinetochores) and α-tubulin." (PMID 20927325, 2010).
colon cancer (2 papers, 2017 to 2020). "Further studies have shown that elevated expression of CENP-A induces genomic instability in pRb-depleted colon cancer cell, and that ectopic expression of CENP-H induces chromosomal missegregation and aneuploidy, suggesting a crucial role of CENPs as mediator during mitosis." (PMID 27974707, 2017).
hepatocellular carcinoma (2 papers, 2021 to 2025). A malignant tumor that arises from hepatocytes. "In recent years, several studies have revealed that several CENPs were aberrantly expressed in hepatocellular carcinoma (HCC)." (PMID 34457090, 2021).
Cirrhosis (1 paper, 2021). A chronic disorder of the liver in which liver tissue becomes scarred and is partially replaced by regenerative nodules and fibrotic tissue resulting in loss of liver function. "Furthermore, the expression of CENPs in patients with cirrhosis has not been reported, which may help to reveal the mechanism of CENPs and HCC." (PMID 34457090, 2021).
malignant lymphoma (1 paper, 2020). "Encouraged by these results, CENPs appeared to be a great potential candidate nanoplatform for photodynamic therapy of malignant lymphoma." (PMID 33240803, 2020).
cancer (19 papers, 2009 to 2025). A tumor composed of atypical neoplastic, often pleomorphic cells that invade other tissues. "Centromere-associated proteins (CENPs) have been reported to be biomarkers for many cancers, but their roles in ESCC have seldom been investigated." (PMID 35496042, 2022). "On the other hand, chromosomal and genetic instability are now recognized as the important cause of cancer, and the abnormal expression of CENPs is likely to play important roles through this mechanism." (PMID 34457090, 2021). "CENPs are also associated with responses to cancer therapy and may affect patient survival." (PMID 37479754, 2023). "Indeed, many researchers have confirmed that the dysregulation of CENPs is significantly associated with cancer prognosis and may serve as a biomarker for non-small-cell lung cancer and breast cancer." (PMID 35496042, 2022). "In recent years, multiple studies have revealed the significant role of CENPs in cancer development and progression." (PMID 41425594, 2025). "CENPs have been shown to be potential targets for cancer therapy, with CENP-E being proposed as a potential target even before its relationship with ovarian cancer was revealed, leading to the development of chemical inhibitors for CENP-E." (PMID 38890751, 2024). "It has been demonstrated that the abnormal expression or activation of CENPs plays a significant part in cancer tumorigenesis and progression." (PMID 33833984, 2021). "Aberrant expression of CENPs has reportedly been related to several human cancers." (PMID 35496042, 2022). "CENPs dysregulation have been reported in some cancers tissues or cell lines." (PMID 20021663, 2009). "We investigated the mRNA levels of 15 CENPs in the tumor and normal tissues of HCC and other major cancers by using Oncomine database." (PMID 34457090, 2021). "Some CENPs, such as CENP-A, CENP-E, CENP-H, and CENP-R, are highly expressed in many cancers and may serve as potential biomarkers for malignant progression and poor prognosis." (PMID 38890751, 2024).
tumor (12 papers, 2004 to 2025). "Currently, numerous studies have shown that CENPs are abnormally expressed in tumor cells and are associated with patient prognosis." (PMID 39915786, 2025). "Moreover, CENPs regulate the tumor mutational burden and microsatellite instability and are associated with tumor immunity and chemotherapy sensitivity." (PMID 40387105, 2025). "CENPs play important roles in centromere function and mitosis and can regulate tumor cell proliferation." (PMID 37479754, 2023). "The later sections revealed a similarly higher accumulation of CENPs in tumor vascular." (PMID 33240803, 2020). "In this strategy, PDT is a trigger for the TF cascade to recruit more CENPs into a tumor." (PMID 33240803, 2020). "However, many CENPs with an abnormal expression were found in tumor cells." (PMID 34457090, 2021). "Notably, obvious tumor suppression was observed in mice treated with ENPs/CENPs plus PDT." (PMID 33240803, 2020). "Then, we selected 4 CENPs (CENPL, CENPQ, CENPR, and CENPU) with high expression in HCC as shown in both the Oncomine and GEPIA databases to further analyze the relationship between mRNA levels and tumor stages." (PMID 34457090, 2021). "Moreover, the increase in local nanoparticles in the CENPs plus PDT group was the most obvious and had a long retention time in the tumor tissue where the fluorescence signal was maintained for 24 h." (PMID 33240803, 2020).
CENPS also shares sentences with these, for which no sentence is quoted: telangiectasis (2 papers); B-cell lymphomas (1); benign prostatic hyperplasia (1); bladder cancer (1); breast carcinoma (1); cervical cancer (1); esophageal squamous cell carcinoma (1); glioma (1); infection (1); liver cancer (1); metastatic disease (1); metastatic prostate carcinoma (1); myxofibrosarcoma (1); non-small cell lung carcinoma (1); osteosarcoma (1); pheochromocytoma (1); prostate carcinoma (1); renal cell carcinoma (1); scleroderma (1); Sjögren's syndrome (1); Telangiectasia (1); teratoma (1); Wilms' tumours (1).